HELLS (helicase, lymphoid specific)
Description:
ATP-dependent chromatin remodeler that regulates chromatin accessibility, DNA methylation, and histone modifications. It facilitates de novo DNA methylation at repetitive sequences and promotes transcriptional silencing via recruitment of DNA methyltransferases (DNMTs) and histone deacetylases (HDACs), contributing to heterochromatin formation and repression of transposable elements. Also involved in DNA repair by recruiting DNA damage response mediators to double-strand breaks in heterochromatin, promoting homologous recombination via RBBP8/CtIP-dependent end resection. During meiosis, it is recruited by PRDM9 to recombination hotspots, aiding chromatin opening. Through these diverse roles, is crucial for processes such as development, differentiation, and genomic stability. Involved in regulation of the expansion or survival of lymphoid cells (By similarity).
Synonyms: LSH; SMARCA6; PASG; Nbla10143; SALNR; ICF4
Tractability: Small molecule: a structure with a bound ligand is known. PROTAC: ubiquitination databases record sites on it.
Target class: Enzyme; Hydrolase
Gene: Protein-coding gene on chromosome 10 (94,545,329 to 94,613,905, forward strand). Ensembl gene ENSG00000119969.
Subcellular location: Nucleus; Chromosome
Subcellular location (Human Protein Atlas): Nucleoplasm; Golgi apparatus; Vesicles
Pathways (Reactome):
Signal Transduction: TGFBR3 expression
Gene Ontology:
Molecular function: chromatin-protein adaptor activity; protein binding; ATP hydrolysis activity; ATP-dependent chromatin remodeler activity; chromatin binding; ATP binding
Biological process: double-strand break repair via homologous recombination; DNA methylation-dependent constitutive heterochromatin formation; double-strand break repair; kidney development; lymphocyte proliferation; negative regulation of gene expression via chromosomal CpG island methylation; pericentric heterochromatin formation; chromatin organization
Cellular component: chromosome; nucleus; pericentric heterochromatin; site of double-strand break; chromosome, centromeric region
Genetic constraint (gnomAD): Loss-of-function variants: 15 observed, 39.32 expected, observed/expected ratio (o/e) 0.38, 90% interval 0.25 to 0.59. The upper end of that interval is the gene's LOEUF score, 0.59, which puts it in group 2 of 6, group 1 being the genes least tolerant of losing a copy. Missense variants: 254 observed, 399.28 expected, observed/expected ratio (o/e) 0.64, 90% interval 0.57 to 0.71. Synonymous variants: 150 observed, 136.16 expected, observed/expected ratio (o/e) 1.1, 90% interval 0.96 to 1.26.
Gene-disease validity (ClinGen):
ClinGen rates the evidence that HELLS causes each of these diseases.
immunodeficiency-centromeric instability-facial anomalies syndrome 4 (autosomal recessive): Moderate.
Homologues: Orthologues: chimpanzee HELLS (99% identical), macaque HELLS (99% identical), dog HELLS (95% identical), rabbit HELLS (94% identical), guinea pig HELLS (93% identical), rat Hells (92% identical), mouse Hells (89% identical), pig HELLS (79% identical), tropical clawed frog hells (72% identical), zebrafish hells (65% identical). Paralogues in human: SMARCA1 (35% identical), SMARCA5 (34% identical), INO80 (34% identical), SMARCA4 (30% identical), CHD2 (30% identical), CHD1 (30% identical), CHD5 (30% identical), SMARCA2 (30% identical), CHD4 (29% identical), CHD3 (29% identical), CHD7 (29% identical), CHD8 (29% identical), and 18 more.
Diseases named in the same sentence as HELLS in open-access papers:
HELLS is named in the same sentence as 54 diseases in open-access papers, as found by Europe PMC text mining. Sharing a sentence is not in itself a finding about the gene and the disease. The quoted sentences say what the papers report.
ICF syndrome (18 papers, 2017 to 2025). "In summary, mutations in DNMT3b, ZBTB24, CDCA7, and HELLS disturb the normal process of DNA methylation, which is critical to the pathogenesis of ICF syndrome." (PMID 39376563, 2024). "The CDCA7/HELLS chromatin remodeling complex, which is mutated in ICF syndrome, contributes to centromeric/pericentromeric stability plausibly by facilitating the replication‐uncoupled process." (PMID 33960584, 2021). "The human HELLS protein is a Snf2-like chromatin remodeller family member and is mutated or misregulated in several cancers and some cases of ICF syndrome." (PMID 31802118, 2020). "Mutations of the chromatin remodeling protein Lsh/HELLS can cause the human Immunodeficiency, Centromere instability and Facial anomalies (ICF) syndrome, which is associated with neurologic deficiencies." (PMID 28442710, 2017). "In humans, patients with ICF syndrome (immunodeficiency, centromere function and facial abnormalities) have mutations in HELLS, the DDM1 orthologue, or in other genes required for DNA methylation, and HEK293 cells mutant for these genes have defects in chromosome segregation and DNA methylation." (PMID 39223305, 2024). "After the identification of CDCA7 and HELLS in 2015 as causative genes of ICF syndrome, the outline of the molecular pathogenesis regarding the chromosome instability observed in this syndrome has been largely unveiled, although further detailed studies are required." (PMID 33960584, 2021). "A striking example was the discovery of mutations in factors of unknown function but devoid of DNMT activity, namely ZBTB24, CDCA7 and HELLS, as genetic causes of the ICF syndrome." (PMID 33916664, 2021). "Notably, HELLS mutations have been identified in ICF syndrome, which is characterized by genomic rearrangements in heterochromatic pericentromeric regions." (PMID 31802118, 2020). "Mutations in both HELLS and CDCA7 have been found to disrupt normal DNA methylation patterns, which cause the progression of ICF syndrome." (PMID 39376563, 2024). "Mutations in HELLS, its activator CDCA7, and the de novo DNA methyltransferase DNMT3B, cause immunodeficiency-centromeric instability-facial anomalies (ICF) syndrome, a genetic disorder associated with the loss of DNA methylation." (PMID 37769127, 2023). "Although the relationships of ZBTB24, CDCA7, and HELLS with DNA methylation are not completely understood, the similarities between ICF syndrome types indicate a possible role for the different genes in the same molecular pathway." (PMID 31963661, 2020). "Pathogenic variants in four genes have been shown to cause ICF syndrome: DNMT3B (ICF1), ZBTB24 (ICF2), CDCA7 (ICF3), and HELLS (ICF4)." (PMID 31066130, 2019). "ICF syndrome patients can be classified based on the impaired gene, in addition to DNMT3B (ICF1): ZBTB24 (zinc-finger and BTB domain-containing 24, ICF2), CDCA7 (cell division cycle-associated 7, ICF3), and HELLS (helicase, lymphoid-specific, ICF4)." (PMID 31963661, 2020). "Pathogenic variants in four genes have been identified to cause ICF syndrome: DNA methyltransferase 3B gene (DNMT3B; ICF1), Zinc-finger and BTB domain-containing 24 gene (ZBTB24; ICF2), cell division cycle associated 7 gene (CDCA7; ICF3) and helicase lymphoid specific gene (HELLS; ICF4)." (PMID 39167297, 2024). "Mutations in lymphoid-specific helicase (HELLS) and cell division cycle associated 7 (CDCA7) can cause a genetically heterogeneous autosomal recessive disorder referred to as centromeric instability and facial anomalies (ICF) syndrome, which is characterized by life-threatening immunodeficiency." (PMID 36032672, 2022). "Hence, we propose that hypomethylation due to inefficient DNMT1/UHRF1 recruitment at pericentromeric repeats by defects in the CDCA7/HELLS complex could induce pericentromeric instability, which may explain a part of the molecular pathogenesis of ICF syndrome." (PMID 33082427, 2020).
lung carcinoma (15 papers, 2020 to 2025). "HELLS is upregulated in lung cancer tissues, and the increased levels are associated with poor overall survival in lung cancer patients." (PMID 36012581, 2022). "Overexpression of HELLS is correlated with the prognosis of lung cancer, indicating that HELLS may be a potential diagnostic biomarker for lung cancer." (PMID 35087751, 2021). "The present study screened several DEGs in three datasets to reveal that increased levels of HELLS mRNA were significantly associated with poor OS in lung cancer patients, suggesting that HELLS may be a potential novel predictor of prognosis." (PMID 32195055, 2020). "HELLS is overexpressed in colorectal, HCC, nasopharyngeal, and lung cancers, leading to poorer prognosis, and therefore, HELLS can be useful as a prognostic marker in various cancers." (PMID 37187896, 2023). "To further assess the expression of ICAM1 and HELLS, we measured mRNA levels in 79 cases of lung cancer and paired paracancer samples." (PMID 32195055, 2020). "Previous studies have revealed that HELLS, an enzyme involved in chromatin remodeling, is overexpressed in numerous types of cancer, including hepatocellular carcinoma, pancreatic cancer, and lung cancer." (PMID 38047020, 2023). "YY1, RTN4, RICTOR, SFPQ, LARP6, and HELLS have been associated with cancers previously and, in this study, exhibited differential level changes between control, Idiopathic Pulmonary Fibrosis (IPF) and lung cancer cells." (PMID 37569873, 2023). "Furthermore, HELLS expression was upregulated in lung cancer tumors." (PMID 32195055, 2020). "Among these targets, we have already analyzed three genes (FAM64A; miR-99a target, HELLs; miR-150-3p target, and TRIP13; miR-139-3p target) as oncogenic target molecules regulated by tumor-suppressive miRNAs in lung cancer." (PMID 39337462, 2024). "SFPQ, RTN4, HELLS, RICTOR, and LARP6 have high expression in lung cancer and other cancer cells and tissues." (PMID 37569873, 2023). "The mRNA level of HELLS was evaluated in lung cancer using GEPIA analysis, and the expression of HELLS in lung cancer tissues was significantly higher than in adjacent tissues (p < 0.05)." (PMID 32195055, 2020). "Lymphoid-specific helicase (HELLS), belonging to the SNF2 family of chromatin remodeling enzymes, has previously demonstrated elevated expression in multiple cancer types, including colorectal cancer, hepatocellular carcinoma (HCC), and lung cancer." (PMID 38047020, 2023). "HELLS, a member of the SNF2 family of chromatin remodeling enzymes, was previously suggested to be overexpressed in various cancer types, such as colorectal cancer, HCC, nasopharyngeal carcinoma, and lung cancer." (PMID 33280236, 2021). "In conclusion, we used integrated bioinformatics analysis to identify candidate genes and pathways in lung cancer to show that HELLS and ICAM1 might be the key genes related to tumorigenesis or tumor progression in lung cancer." (PMID 32195055, 2020). "Finally, we analyzed the expression of HELLS and ICAM1 in lung cancer patients to determine their expression patterns, potential functions, and different prognostic values." (PMID 32195055, 2020). "Helicase, Lymphoid-Specific (HELLS) and Intercellular adhesion molecule 1 (ICAM1) were identified, and their biological functions and key pathways were enriched to ascertain more accurate and practical biomarkers for the early diagnosis, individualized prevention, and treatment of lung cancer." (PMID 32195055, 2020).
hepatocellular carcinoma (14 papers, 2019 to 2025). A malignant tumor that arises from hepatocytes. "HELLS has been implicated in many types of cancer, including retinoblastoma, colorectal cancer, hepatocellular carcinoma, and glioblastoma." (PMID 36012581, 2022). "Mutations or overexpression of HELLS have been associated with many types of cancer, including leukemia, retinoblastoma, colorectal cancer, hepatocellular carcinoma (HCC), and glioblastoma." (PMID 36012581, 2022). "Mutations or overexpression of Helicase, lymphoid specific (HELLS), a member of the ATP-dependent chromatin remodeling SNF2 family, have been linked to various cancers, including CRC, hepatocellular carcinoma, and leukemia." (PMID 40547309, 2025). "In hepatocellular carcinoma, HELLS is involved in chromatin remodeling and epigenetic silencing, thus promoting tumor proliferation and metastasis." (PMID 35912252, 2022). "HELLS overexpression can also promote the growth of hepatocellular carcinoma by activating the transcription of centromere protein F." (PMID 35774795, 2022). "Overexpression of HELLS was reported in several types of cancers, e.g., nasopharyngeal carcinoma, hepatocellular carcinoma, colorectal cancer and pancreatic cancer." (PMID 34944699, 2021). "Helicase lymphoid specific (HELLS, known as LSH), a chromatin remodeler, was shown to be linked with advanced stage and worse prognosis in pancreatic carcinoma, hepatocellular carcinoma, and nasopharyngeal carcinoma." (PMID 34335745, 2021). "Significant overexpression of HELLS has been found in various cancers, including medulloblastoma, hepatocellular carcinoma (HCC), and CRC." (PMID 34315468, 2021). "Genes, such as CHAF1B, INHBA, TGFB2, SKA3, and HELLS, are responsible for the invasion of various cancer cells, such as hepatocellular carcinoma, gastric cancer cells, renal cell carcinoma, prostate cancer, head and neck cancer, but these genes may be involved in the invasion of BRCA cells." (PMID 31311202, 2019). "In hepatocellular carcinoma (HCC), HELLS overexpression has been shown to mediate epigenetic silencing of tumor suppressor genes by increasing nucleosomal occupancy at promoters and enhancers, thereby limiting the accessibility of the regions." (PMID 32840881, 2021). "Similarly, Law’s team observed decreased growth and metastatic ability of hepatocellular carcinoma (HCC) in both in vitro and in vivo experiments by knocking down the deconjugating enzyme HELLS (Helicase Lymphoid-Specific), which revealed the critical role of epigenetic factors in tumor progression." (PMID 40697666, 2025).
retinoblastoma (13 papers, 2014 to 2023). A malignant tumor that originates in the nuclear layer of the retina. "HELLS is a gene whose transcription is controlled by the RB/E2F pathway, which is believed to be the cause of epigenetic changes in retinoblastoma and is necessary for tumor production." (PMID 33889544, 2021). "Despite the apparent dispensable role of HELLS in retinal development, here we present evidence that loss of HELLS significantly decreases the incidence of retinoblastoma, delays tumor progression, and increases overall survival." (PMID 32071286, 2020). "Together with the nontoxic effect of HELLS loss in the developing retina, our results suggest that HELLS and its downstream pathways could serve as potential therapeutic targets for retinoblastoma." (PMID 32071286, 2020). "For instance, numerous studies showed that the presence of many dysregulation CRs (e.g., UHRF1, DNMT1, EZH2, BMI1 and HELLS) might lead to an abnormal epigenetic landscape in retinoblastoma (RB), which might be associated with tumorigenesis and malignant progression." (PMID 36318256, 2023). "Inactivation and loss of RB1 results in overexpression of HELLS and increased proliferation of retinoblastoma tumors; HELLS has therefore emerged as a potential new therapeutic target for retinoblastoma." (PMID 36012581, 2022). "In a genetic mouse model of retinoblastoma, targeting HELLS decreased cellular proliferation, tumorigenesis, and morbidity and increased survival." (PMID 36012581, 2022). "Transcriptome profiles revealed gradual development of a retinoblastoma expression signature in RB1ko with upregulation of proliferation-associated genes and retinoblastoma-related oncogenes such as DEK, SYK and HELLS." (PMID 35565295, 2022). "Plotting the expression of genes known to be associated with retinoblastoma development, such as MDM2, DEK, SYK and HELLS, confirmed their upregulation in RB1ko when compared to RB1wt and RB1het and in the tumor specimens." (PMID 35565295, 2022). "In retinoblastoma, HELLS overexpression is critical for ectopic proliferation and tumor progression." (PMID 33003565, 2020). "In spite of the dispensable role of HELLS during retinal development, genetic ablation of Hells in a genetically engineered mouse model of retinoblastoma led to a drastic increase in survival and decrease in morbidity compared to littermate controls." (PMID 32426419, 2020). "Recent studies have shown that HELLS genes are upregulated in nasopharyngeal carcinoma, retinoblastoma, head and neck cancer, and breast cancer." (PMID 32195055, 2020). "We found that HELLS abrogation during retinoblastoma development leads to a significant decrease in morbidity and increase in survival." (PMID 32071286, 2020). "HELLS is also transcriptionally regulated by the pRB/E2F pathway and overexpressed in multiple types of cancer, including retinoblastoma." (PMID 33003565, 2020). "A previous study in retinoblastoma identified HELLS as a key target gene that promotes tumor proliferation." (PMID 32071286, 2020). "A previous study in retinoblastoma identified HELLS as a key target gene downstream of the RB-E2F signaling pathway that is overexpressed following the loss of RB, and contributes to tumorigenesis." (PMID 30220967, 2018). "UHRF1 and HELLS knockdown in both control and retinoblastoma cell lines led to a significant reduction in colonies formed compared to the lenti-GFP controls." (PMID 25338120, 2014). "Furthermore, in retinoblastoma cells, ubiquitin-like, containing PFD and RING finger domains 1 (UHRF1) and helicase, lymphoid specific (HELLS) are overexpressed, which is linked to epigenetic activation of SYK." (PMID 34359636, 2021). "Similar to what we observed in retinoblastoma, depletion of HELLS in glioblastoma and several carcinomas impairs tumor growth, suggesting that HELLS may contribute to the malignant progression of various tumors." (PMID 32426419, 2020).